LEF1 (lymphoid enhancer binding factor 1)
Diseases named in the same sentence as LEF1 in open-access papers (continued):
Sharing a sentence is not in itself a finding about the gene and the disease.
tumor (continued). "Although these signatures were excluded from this study, these may be important because TGFβ and LEF1 signatures are involved in epithelial‐to‐mesenchymal transition (EMT) and NFκB and RELA signatures are involved in tumor immunity." (PMID 29862663, 2018). "Since promotion of myodifferentiation can be tumor suppressive in RMS development, we also investigated whether LEF1 is involved in muscle differentiation processes." (PMID 27965462, 2017). "Furthermore, we showed that p300 upregulation on a stiff matrix led to c-Myb acetylation, promoting c-Myb and LEF1 recruitment to the DDR2 promoter and leading to expression of DDR2 and EMT marker genes in the stiff stroma of a developing tumour." (PMID 28754957, 2017). "Because c-MYC drives proliferation of many tumor cells including RMS, it is tempting to speculate that the increased c-MYC levels in ARMS LEF1 KD cells are responsible for induction of proliferation." (PMID 27965462, 2017). "Notably, LEF1 was identified as a regulator of FN1 and CDH1 expression in tumor-derived cells and was proposed to act in both, a CTNNB1-dependent as well as -independent manner." (PMID 23677615, 2013). "Thus, this cooperation between TCF1/LEF1 and ATF2 represents an unexpected new strategy used by tumor cells to aberrantly activate TCF1/LEF1 signaling independently of β-catenin and the Wnt canonical pathway." (PMID 23966864, 2013). "Both univariate and multivariate analyses identified stage (p<0.0001) and LEF1 overexpression (p<0.05) as important prognostic markers, but not tumor grade or SPP1." (PMID 21383983, 2011). "Using microarray analysis, we identified three novel markers of the tumor-initiating PC3 holoclones and spheres, which showed either increased expression (FAM65B) or decreased expression (MFI2 and LEF1) in both holoclones and spheres compared to paraclones and parental PC3 cells." (PMID 21190562, 2010). "PC3 tumors seeded with holoclones showed dramatic down regulation of FAM65B and dramatic up regulation of MFI2 and LEF1, and unexpectedly, a marked increase in tumor vascularity compared to parental PC3 tumors, suggesting a role of cancer stem cells in tumor angiogenesis." (PMID 21190562, 2010). "Simultaneous detection of LEF-1 and HBsAg was observed in HBsAg positive HCC tissues and, additionally, the simultaneous detection of HBsAg and LEF-1 was more pronounced in peritumor tissues, compared to that in the tumor tissues." (PMID 19402906, 2009). "Lef-1/β-catenin precipitates were also found in malignant ovarian cancer, but without concomitant staining in the nucleus of the tumour cells." (PMID 14520463, 2003). "In the LEF1-negative expression group, four patients all showing LEF1 staining in 10–30% of tumor cells, with no β-catenin immunoreaction or focal β-catenin membranous staining, suggesting that focal LEF1 expression may have diagnostic significance for BA." (PMID 39881334, 2025). "In OSCC, LEF1 is overexpressed in tumour tissues compared to non-tumorous oral mucosa." (PMID 37553362, 2023). "Notably, all sequenced DIAMOND tumours show a consistent upregulation of Ctnnb1 and Lef1, while Tcf7l2 is not differentially regulated." (PMID 37907668, 2023). "Moreover, AhR deficiency inhibited, rather than enhanced, tumor formation and tumor-derived organoids in Apc-deficient cells both in vivo and in vitro by activating Wnt/β-catenin signaling and TCF4/LEF1-dependent transcription." (PMID 37781044, 2023). "AHCY deficiency’s impact on methylation capacity may have downstream effects on gene expression, possibly influencing the Wnt signaling pathway and the role of LEF1 and the formation of the β-catenin/LEF1 complex, which is crucial for Wnt target gene regulation in SW480 tumor cells." (PMID 38003292, 2023).
tumor (continued). "For these 3 LEF-1 diffuse strongly expressed MBs, all showed classic histological feature, and geneticlly defined as WNT-activated MBs, while β-catenin expression was difficult to read, and less than 1% tumor cells showed nuclear β-catenin staining for the 4 positive cases." (PMID 36096860, 2022). "These tumours also displayed high expression levels of epidermal differentiation genes (such as IVL, LOR and KRT1), indicating that these tumours had undergone squamous metaplasia, and an activation of the WNT/β-catenin signalling pathway (expression of WNT10B and LEF1)." (PMID 34916592, 2022). "To check whether β‐catenin is involved in miR‐378a‐3p‐elicited functional effects in HCC, we further analyzed the effect of blocking β‐catenin signaling via siRNA‐mediated knockdown of TCF4 or LEF1 on the proliferative, migratory, and invasive capacity of SMMC‐7721‐antagomiR‐378a‐3p tumor cells." (PMID 33634974, 2021). "This may explain the difference in the transcription of genes regulated by LEF1, but not LEF1 itself in OSA tissue compared to non-tumor tissue." (PMID 32854182, 2020). "Interestingly, we found super-enhancers near not only oncogenes but also tumor suppressor genes (IKZF1, LEF1, RUNX1), implying that not all super-enhancer associated genes contribute to tumor progression." (PMID 30304769, 2018). "Then, to determine whether CWP232228 treatment affects Wnt/β-catenin signaling in vivo, we investigated the expression patterns of its signaling components, Wnt1, LEF1, and β-catenin in tumor tissues of mice with or without CWP232228 treatment." (PMID 26967248, 2016). "Notably, negative or positive correlation between HPSE and Smad4 or LEF1 expression was observed in different NB and neuroblastic tumor cohorts." (PMID 27595937, 2016). "While acknowledging unusual examples such as LEF-1, one would expect that, in the majority of cases, IRES function is likely to be of most relevance when cap-dependent translation is compromised, e.g., following exposure to chemotherapeutic agents and in a hypoxic tumor cell environment." (PMID 26734574, 2015). "Also in these tumor cells, PI3K inhibition dose dependently reduced β-Catenin transcriptional activity and readily reduced the expression of the WNT target genes c-MYC, Cyclin-D1 and notably LEF-1." (PMID 24930890, 2014). "Moreover, we further analyzed whether the reduced tumor cell viability is due to induction of apoptosis and found that SW480 and SW620 cells with stable LEF1 shRNA transfection had significantly more apoptosis compared to the control cells." (PMID 24098538, 2013). "Though our analysis focused primarily on LEF1 and SPP1, other highly-ranked signature genes with increased expression in CLM compared to primary CRC also have biological functions consistent with roles in tumor progression, and might have prognostic utility." (PMID 21383983, 2011). "In addition, independent of tumor stage, overexpression of LEF1, not SPP1, denotes a poor prognosis for survival." (PMID 21383983, 2011). "As LEF-1 has been shown to be a target of TCF4/β-catenin, we speculated that tumour progression may be accompanied by a shift of β-catenin binding partners from TCF4 to LEF1 and we therefore expected to find TCF4 positivity mainly in central tumour areas and LEF-1 mainly in the front of invasion." (PMID 21092222, 2010). "As LEF1 expression was found more often in main tumour areas and correlated with better survival it might indicate differentiated tumor cells without invasive or metastatic potential." (PMID 21092222, 2010). "Up-regulation of 38 kDa dominant negative isoform of LEF-1 in tumor cells could suppress rather than activate the Wnt pathway." (PMID 19402906, 2009). "Notably, the CD8_Tem-GZMK subset was relatively closer to the CD8_Tex-LAYN subset compared to the CD8_Tn-LEF1 and CD8_Trm-KLRB1 subsets, aligning with recent studies that highlight the transition from effector memory T cells to exhausted T cells during tumor progression." (PMID 38596689, 2024).
tumor (continued). "We suspect that LEF1 recruits KDM4A/N-CoR and may recruit other epigenetic modification complexes to maintain the homeostasis of histone modifications at target promoters, thereby transcriptionally suppressing tumour-suppressor genes such as LATS2 and inhibiting the progression of OSCC." (PMID 37553362, 2023). "However, silver staining of the gel for the immunoprecipitates after transfer revealed a band with a molecular weight of approximately 300 kDa in the adenocarcinoma, suggesting APC as an interacting partner with β-catenin in this tumour, in addition to Lef-1 (data not shown)." (PMID 14520463, 2003). "On histopathological evaluation, the immunohistochemical analysis showed that tumor cells exhibited positive staining for cytokeratin 7 (CK7), lymphoid enhancer-binding factor 1 (LEF1), calponin, and s100 (focal) while negative for GATA3 and TTFl." (PMID 40078247, 2025). "In the fetal-I and II tumor organoids, HNF4A expression was consistently observed throughout, while LEF1 expression was generally absent." (PMID 39567475, 2024). "This suggests LEF1 as a prime, although not exclusive candidate, through which IGF2BP1 promotes mesenchymal-like tumor cell properties." (PMID 23677615, 2013). "When the expression of LEF-1 protein was compared with that of HBV negative normal liver tissues, marked up-regulation of LEF-1 was observed both in tumor tissues and the peri-tumor tisseus among all of 30 HCC tissues." (PMID 19402906, 2009). "LEF-1 staining significantly correlated with CTNNB1 staining (R2= 0.1283, p= 0.0046), although with discrepancies at the individual sample level as these were not consecutive slides of the tumour." (PMID 40130164, 2025). "However, a 38 kDa truncated isoform of LEF-1, rather than the 55 kDa wild-type LEF-1, was significantly elevated in the HBsAg positive tumor cells." (PMID 19402906, 2009). "In BCPAP cells treated for 72 h, genes from the canonical Wnt pathway (FZD1, DVL1, AKT2, CTNNB1, LEF1, MYC) and the non-canonical Wnt pathway (RHOA, related to cytoskeletal dynamics and increased migration and invasion) were upregulated, suggesting pro-tumor behavior." (PMID 39125748, 2024).
cancer (192 papers, 2007 to 2025). A tumor composed of atypical neoplastic, often pleomorphic cells that invade other tissues. "Numerous studies have reported that aberrant expression of LEF1 is associated with tumorigenesis, as well as cancer cell proliferation, migration, and invasion, and its overexpression has been linked to poor prognosis." (PMID 40918098, 2025). "Increased LEF1 expression has been associated with carcinogenesis in many different cancer types, including melanoma, pancreatic, colorectal, and breast, as well as several myeloid and blood cancers." (PMID 38792023, 2024). "Among these disease pathways, the upregulated genes were predominantly enriched within the cell proliferation module of cancer-associated pathways, including Lef1, Tcf7l1, and Myc genes." (PMID 39408685, 2024). "There are many articles in the literature that underline the role of LEF1 as a transcription factor and, therefore, its increased presence in cancer." (PMID 39200196, 2024). "β-catenin and LEF1 are key mediators of Wnt signaling, and their dysregulation is a hallmark of many cancer types." (PMID 37371581, 2023). "Dysregulation of β-catenin and LEF1 is a common feature in many types of cancer, highlighting the importance of understanding the underlying mechanisms of their regulation." (PMID 37371581, 2023). "LEF1 is an important downstream mediator of the Wnt/β-catenin signaling pathway and has been linked to carcinogenesis, cancer proliferation, migration, and invasion." (PMID 37106379, 2023). "Abnormal expression and activity of the transcription factor LEF1 have been implicated in tumorigenesis, and LEF1 plays a key role in regulating various cancer-related processes, such as EMT, cancer cell proliferation, migration, invasiveness, and cell death." (PMID 37047688, 2023). "This included the probe cg03041109 in the body of LEF1, which was significantly associated with cancer status (FDR = 0.02)." (PMID 37377903, 2023). "They believed that Presenilin-1 is associated with CAJ disassembly and can drive cancer progression by triggering TCF / LEF-1 activation." (PMID 36117156, 2022). "LEF1 is a transcription factor involved in the Wnt/β-catenin signaling pathway and is implicated in oncogenesis and progression of cancer." (PMID 34639214, 2021). "One of the most enriched pathways for downregulated genes was “Pathways in cancer-hsa05200,” which is consistent with the association of LEF1 expression with a variety of cancers." (PMID 32586085, 2020). "Our findings suggest that EBV epigenetically reprogrammed epithelial cells with features of basal, wound healing keratinocytes, with LEF1 contributing to the metastatic phenotype of EBV-associated carcinomas." (PMID 29535816, 2018). "Furthermore, we leveraged the noncoding genome and methylome to identify inherited epimutations in genes including ASXL1, ETV6, and LEF1 that confer increased cancer risk." (PMID 37377903, 2023). "Furthermore, we evaluated the noncoding genome and methylome and identified inherited epimutations in genes including ASXL1, ETV6, and LEF1 that confer increased cancer risk." (PMID 37377903, 2023). "Abnormal expression of LEF1 has been implicated in the proliferation and apoptosis of several cancer cells, and LEF1-mediated gene transcription may go beyond the Wnt-β-catenin pathway." (PMID 37553362, 2023). "LEF1, a protein encoded by the LEF1 gene in humans, has shown its expression in several cancers." (PMID 35885958, 2022). "Aberrant expression of Lef1 has been associated with poor prognosis in several cancers." (PMID 32492961, 2020). "Increased LEF1 expression is associated with several types of cancer and has been associated in many tissues with regulation of epithelial-to-mesenchymal transition (EMT) including transcriptional activation of EMT effectors, such as N-Cadherin, Vimentin, and Snail." (PMID 32403323, 2020).
cancer (continued). "While LEF1 is involved in physiological processes, such as stem cell maintenance, lymphocyte differentiation and proliferation, and organ development, including mammary glands, that requires inductive epithelial–mesenchymal interactions, it is also implicated in cancer development and malignancy." (PMID 39887653, 2025). "We observed nuclear LEF1‐positive, elongated spindle‐shaped cells near the areas occupied by cancer cells." (PMID 39887653, 2025). "Aberrant Lef1 transcription is involved in tumorigenesis, as well as cancer cell proliferation, migration, and invasion." (PMID 41459157, 2025). "Abnormal expression of LEF1 is related to tumorigenesis and proliferation, migration, and invasion of cancer cells." (PMID 39744480, 2025). "To corroborate this, we assessed the expression levels of genes in AP-1, NF-κB, ASCL2, and LEF1 regulons across the cancer states." (PMID 40393458, 2025). "We further investigated the effect of LEF1 suppression in the exp‐CAFs on cancer cell proliferation and neoangiogenesis." (PMID 39887653, 2025). "The authors developed O’PROTACs targeting lymphoid enhancer-binding factor 1 (LEF1) and the ETS-related gene (ERG), two transcription factors highly implicated in cancer." (PMID 40507351, 2025). "To understand the dynamics of exhausted T cells, we examined the relationship between the expression of the stem-like markers Tcf7, Slamf6, Lef1, and Bach2 and the exhaustion markers across the pan-cancer dataset." (PMID 40076932, 2025). "We previously discussed the current landscape of drugs targeting the Wnt/β-catenin/LEF1 pathway in cancer, including the challenges involved in successfully targeting this pathway due to its crucial physiological role in the body." (PMID 40566602, 2025). "LEF1 expression has also been shown to be downregulated in numerous cancers through promoter hypermethylation and also higher levels of IRF8." (PMID 38792023, 2024). "The results revealed that DD-9 can effectively reduce the mRNA expression of β-catenin and its target genes cyclin D1 and LEF1 and inhibit their transcription level, compared to that in the control group in tested cancer cells." (PMID 38921589, 2024). "Hereon, our research revealed that PACAP38 downregulated the crucial effector (β-catenin), nuclear transcription factors (LEF1, TCF1/TCF7), and downstream target genes (MMP7, cJUN, c-myc and CD44) associated with the Wnt/β-catenin signaling in cancer cells." (PMID 39619607, 2024). "A large number of other small molecule inhibitors targeting the Wnt/beta-catenin/LEF1 pathway have since been discovered, and work to improve their utility and specificity as anti-cancer treatments is ongoing." (PMID 38792023, 2024). "We also explored the biologicalfunctions and molecular mechanisms related to these transcription factors, aiming toprovide a comprehensive understanding of the relevance of the LEF1/TCF family inbreast cancer." (PMID 38100720, 2023). "Not only is LEF1 at the center of signaling pathways and mechanisms that initiate and maintain carcinogenesis, the suppression of LEF1 reduces the proliferative and invasive properties of cancer." (PMID 38003292, 2023). "Dysregulation of LEF1 has been observed in various cancer cells, suggesting its potential as a marker for cancer diagnosis and prognosis." (PMID 37657935, 2023). "Dysregulation of LEF1 contributes to the progression of multiple cancers, including breast, colon, prostate, and oesophageal squamous cell carcinoma." (PMID 37553362, 2023). "LEF1 has been reported to promote EMT in cancer cells by activating Wnt/β-catenin signaling, which can in turn activate Notch signaling and GPCR signaling." (PMID 38003292, 2023).